ENSG00000252904
Synonyms: LOC124900212
Gene: Small nucleolar RNA gene on chromosome 5 (65,961,183 to 65,961,319, reverse strand). Ensembl gene ENSG00000252904.
Gene Ontology:
Biological process: RNA processing
Cellular component: nucleolus
Homologues: Orthologues: rat LOC120102740 (46% identical), rat LOC120099521 (45% identical), mouse Gm26047 (43% identical), rat LOC120096832 (43% identical), rat LOC120098405 (43% identical), rat LOC120100468 (43% identical), mouse Gm23786 (42% identical), rat LOC120096123 (40% identical), rat LOC120098008 (34% identical), rat Snora50d (33% identical). Paralogues in human: SNORA50D (48% identical), SNORA50C (46% identical), SNORA50B (37% identical), SNORA50A (34% identical).